RNU1-146P (RNA, U1 small nuclear 146, pseudogene)
Gene: Small nuclear RNA gene on chromosome 12 (19,724,435 to 19,724,599, forward strand). Ensembl gene ENSG00000200885.
Homologues: Orthologues: chimpanzee U1 (99% identical), macaque U1 (82% identical), guinea pig U1 (79% identical), rabbit U1 (79% identical), rat LOC120098052 (74% identical), dog U1 (67% identical). Paralogues in human: RNU1-11P (82% identical), RNU1-1 (82% identical), RNU1-2 (82% identical), RNU1-27P (82% identical), RNU1-28P (82% identical), RNU1-3 (82% identical), RNU1-4 (82% identical), RNU1-56P (82% identical), RNU1-67P (82% identical), RNVU1-18 (82% identical), RNVU1-29 (82% identical), RNVU1-31 (82% identical), and 134 more.